RYR2 (ryanodine receptor 2)
Diseases named in the same sentence as RYR2 in open-access papers (continued):
Sharing a sentence is not in itself a finding about the gene and the disease.
heart failure (continued). "Dantrolene inhibits Ca2+ leakage through RyR2 in CPVT or heart failure by allosterically increasing the binding affinity of CaM to RyR224,25." (PMID 33244105, 2020). "Reduced expression of SERCA2a and at least unaltered phosphorylation of RyR2, however, were found in human paroxysmal AF and in rats with hypertensive heart disease and heart failure." (PMID 33265909, 2020). "Recent studies have shown that endoplasmic reticulum Ca2+ leakage via RyR2 channels in cardiomyocytes leads to mitochondrial Ca2+ accumulation and dysfunction in heart failure." (PMID 31143551, 2019). "Abnormal RyR2 function is recognized as an important part of the pathophysiology of heart failure, especially contractile dysfunction, arrhythmia and sudden death." (PMID 30678657, 2019). "Several studies have linked increased SR Ca leak during myocardial infarction and heart failure to the activation of RyR2 in response to oxidative stress." (PMID 30574097, 2018). "In heart failure it is thought that RyR2 channels become abnormally active or “leaky” and are unable to remain closed during diastole." (PMID 28630041, 2017). "Given the essential role of RyR2 channels in excitation-contraction (EC) coupling, it is unsurprising that these channels are key players in heart failure and fatal arrhythmias, where damaging changes to Ca2+ homeostasis occurs." (PMID 28630041, 2017). "T-tubule fragmentation interrupts coupling between LTCCs and RyR2 in the interior of the myocyte, leading to the dyssynchronous Ca2+ release and reduced force generation that typifies heart failure." (PMID 28706255, 2017). "In heart failure models RyR2 channels not only display irregular activity and are open when they should remain closed, but the reported mode of channel gating is also altered." (PMID 28630041, 2017). "Sub-conductance-state gating of RyR2 in heart failure models is thought to be a result of hyperphosphorylation of the channel leading to the dissociation of FKBP12.6." (PMID 28630041, 2017). "Previous studies have suggested that in heart failure RyR2 becomes hyperphosphorylated at serine 2808/2809, which leads to the dissociation of the FK-506-binding protein 1B (FKBP12.6), resulting in sub-state gating." (PMID 28630041, 2017). "Experiments in a mouse model of heart failure generated by myocardial infarction, leaky RyR2 was shown to be responsible for mitochondrial Ca2+ overload." (PMID 27536244, 2016). "The T4 treatment can potentially normalize the levels of T3 as well elevated Serca2 and Ryr2 gene expression in the myocardium in heart failure rats with euthyroid sick syndrome." (PMID 27737323, 2016). "In conclusion, the T4 treatment can potentially normalize the levels of T3 as well elevated Serca2 and Ryr2 gene expression in the myocardium in heart failure rats with euthyroid sick syndrome." (PMID 27737323, 2016). "Our results suggest that a low-dose β1-selective blocker inhibits Ca2+ leakage through RyR2 by selectively suppressing RyR2 phosphorylation during heart failure." (PMID 25614983, 2015). "Increased RyR2 activity and Ca2+ leak are also frequently found in myocytes isolated from animal models of heart failure, and RyR2 hyperactivity likely contributes to ventricular arrhythmia risk." (PMID 26121139, 2015). "Hyper-phosphorylation of the cardiac Ca2+ release channel (RyR2) by PKA at serine-2808 has been proposed to be a key mechanism for cardiac dysfunction in heart failure." (PMID 26154764, 2015). "A series of studies in a rabbit model of non-ischemic heart failure provides further mechanistic evidence of the importance of CaMKII regulation of RyR2 in heart failure arrhythmogenesis." (PMID 24994983, 2014). "Experiments in vitro revealed a major role for S2030 in the control of RyR2 activity, and in heart failure patients, it appeared as a reliable marker of RyR2 dysfunction, presumably even superseding S2808." (PMID 24847270, 2014).
heart failure (continued). "Murine models of heart failure, CaMKII hyperactivity (overexpression), and CaMKII regulation of RyR2 have provided a wealth of information describing how CaMKII contributes to both arrhythmogenesis and disease progression in cardiomyopathy." (PMID 24994983, 2014). "In other studies carvedilol demonstrated a marked beneficial effect in heart failure via scavenging free radicals, preventing Ca2+ leak due to stabilization of RyR2 in hearts with a marked failure." (PMID 23923043, 2013). "Several studies have investigated the preventive role of various β-blockers on the development of heart failure by restoring RyR2 dysfunction." (PMID 23923043, 2013). "In heart failure, enhanced sympathetic nerve excitation leads to increased CaMKII activity, which results in hyperphosphorylation of RyR2." (PMID 23781262, 2013). "On account of these findings, a hyperphosphorylation of RyR2 by PKA had been proposed as central mechanism in the pathogenesis of heart failure." (PMID 22932727, 2013). "Marks and colleagues also found a hyperphosphorylation of RyR2 at S2809 in overt human heart failure." (PMID 22932727, 2013). "The stability of RyR2-closure is severely compromised in heart failure leading to an increased diastolic open probability and thus an increased diastolic leak." (PMID 22932727, 2013). "It has been suggested that there is a reduced amount of FKBP12.6 bound to RyR2 channels in heart failure and that this leads to an increased tendency for SR Ca2+-release events during diastole and an increased likelihood of developing arrhythmias." (PMID 22363773, 2012). "Chronic PKA hyperphosphorylation of RyR2 in heart failure leads to depletion of calcium in SR, which in turn reduces EC coupling gain and contributes to impaired systolic contractility." (PMID 22073308, 2011). "The phosphorylation status of RyR2 in heart failure and its effect on the RyR2-FKBP12.6 interaction are controversial." (PMID 19442077, 2009). "Hyperphosphorylation of RyR2 in heart failure produced by rapid right ventricular pacing is reversed by K201 treatment, with a return to levels of channel phosphorylation seen in normal hearts." (PMID 19442077, 2009). "Our results, in fact, demonstrate that frank heart failure can occur in the context of reduced total RyR2, phosphorylated RyR2 at Serine 2809 and increased SR Ca2+ loading." (PMID 19125184, 2009). "RyR2 dysfunction manifested as tachyarrhythmias is triggered by physical or emotional stress in CPVT patients and similar symptoms causes SCD in ∼50% of heart failure (HF) patients." (PMID 19345240, 2009). "Moreover, the interaction between CaMKII and RYR2 is pivotal in the context of ventricular arrhythmias and heart failure." (PMID 40948388, 2025). "Ca leak in heart failure is dependent on RyR2 structural integrity." (PMID 41278880, 2025). "Since phosphorylation of most Ca2 + -handling proteins is altered in many models of experimental heart failure, which might lead to increased Ca2 + leakage, we compared the effects of PG-LPS on RyR2 phosphorylation at Ser-2814 and Ser-2808." (PMID 40179080, 2025). "In spontaneously hypertensive rats with heart failure, elevated xanthine oxidase activity generated excessive reactive oxygen species (ROS), which competed with S-nitrosylation to modify cysteine residues on the ryanodine receptor 2 (RyR2)." (PMID 40867518, 2025). "For the translation of our approach disrupting mutant RyR2 expression, one concern with older adults is that RyR2 levels may decrease with comorbidities such as diabetes and heart failure, in which case a RyR2 replacement therapy might be needed." (PMID 38464671, 2024). "Specifically, this study demonstrates that SERCA, NCX, and RyR2 dysfunction, along with the downregulation of the cardiomyocyte’s potassium currents, could substantially contribute to heart failure." (PMID 39595549, 2024).
heart failure (continued). "The water-soluble so-called RyCal S107 inhibited both RyR2-mediated Ca2+ leak and stress-induced ventricular arrhythmias in RyR2R2474S/+ mice and reduced heart failure progression in homozygous RyR2S2808D+/+ mice carrying a mutation that mimics PKA hyper-phosphorylation." (PMID 38012000, 2024). "Consequently, our strategy to identify multi-targeted drug compounds with RyR2 inhibitory activity combined with SERCA2a activatory activity is expected to represent a safe approach for treatment of heart failure." (PMID 38012000, 2024). "Our study identified a first multi-targeted compound (GM1869) inhibiting RyR2-mediated Ca2+ leak together with activating SERCA2a function that may represent a critical breakthrough for treatment of diastolic Ca2+ leak in heart failure." (PMID 38012000, 2024). "This might aid a deepened understanding of the molecular S100A1/RyR2 liaison given the therapeutic potential of S100A1 in heart failure." (PMID 38819384, 2024). "However, they suggest that the relative contributions of changes of SERCA and RyR2 to heart failure be reevaluated, which will was done in this study." (PMID 39595549, 2024). "rat cardiomyopathy; Increased functional activity of RyR2 should be related to RyR2 phosphorylation status, which could be contribute part of mechanism of various forms of heart failure and DCM." (PMID 38961333, 2024). "Therefore, β-blockers exert beneficial therapeutic effects food on cardiac tachyarrhythmias and heart failure via modulation of RyR2." (PMID 37509534, 2023). "The organisation of these clusters, and their remodelling on a nanoscale, has recently drawn interest as a mechanism for regulating RyR2 function, which may be altered in cardiac diseases, particularly heart failure (HF)." (PMID 37890552, 2023). "As RyR2 was demonstrated to be depleted of CaM in certain CPVTs and heart failure, EL20 may offer a selective therapeutic mechanism in CPVT and heart failure when CaM binding to RyR2 is low." (PMID 35457253, 2022). "Hyperactive RYR2 channels and an increased rate of spontaneous Ca release have also been observed in ventricular myocytes isolated from failing human hearts and animal models of heart failure." (PMID 34990403, 2022). "Hence, intervention with pharmacologic agents that target RyR2 can prevent arrhythmias not only in CPVT but also in heart failure models." (PMID 34990403, 2022). "Interestingly, in heart failure, phosphorylation of RyR2 (and PLB) was decreased at sites predominantly phosphorylated by Ca2+/calmodulin-dependent protein kinase II (CaMKII) and unchanged at sites predominantly phosphorylated by PKA." (PMID 36231118, 2022). "Similar to heart failure, impaired cardiac function caused by ischemia-reperfusion injury also promotes ROS and NO production, phosphorylation, and dissociation of FKBP12.6 from RyR2." (PMID 34639137, 2021). "Therefore, with the atomic level structures in mind, more rigorous analysis is needed to determine the critical role of inter-domain interactions on RyR2 function in heart failure." (PMID 33244105, 2020). "Ryanodine receptor 2 (RyR2) channels that play a key role in sarcoplasmic reticulum release of calcium with myocyte depolarization are dysfunctional in disease states such as heart failure and atrial fibrillation where the cardiac chambers are known to distend and stretch." (PMID 32714203, 2020). "In heart failure RyR2 channels become inappropriately activated during diastole." (PMID 28630041, 2017). "The role of RyR2 in SR Ca2+ leak in heart failure is widely accepted." (PMID 28630041, 2017). "The cardiac Ryr (Ryr2) contains 89 Cys residues, it has been shown that hyperoxidation of the channel increases its open probability, which makes the channel leaky, a pathophysiological condition predominant in heart failure." (PMID 27777931, 2016). "In heart failure, the difference in phosphorylation level between RyR2 and PLB might arise from the compartmentation of the PKA signaling cascade." (PMID 25614983, 2015).
heart failure (continued). "Although overall calmodulin levels are increased in cAF patients, a reduced affinity between RyR2 and calmodulin, as observed in heart failure, could potentially contribute to RyR2 dysfunction in AF." (PMID 24624086, 2014). "Given the importance of oxidation for the response of RyR2 channels to changes in luminal [Ca2+] in heart failure, we have, for the first time, explored the response of healthy RyR2 channels to physiological changes in luminal [Ca2+] over a range of cytoplasmic redox potentials." (PMID 25146393, 2014). "The RyR2 activity is enhanced also in heart failure, and this presumably contributes toward decreasing calcium content in sarcoplasmic reticulum and inducing calcium release abnormalities observed in heart failure." (PMID 24141185, 2013). "The redox state of RyR2 is altered in heart failure, leading to enhanced RyR2 activity, which presumably contributes to decrease SR calcium content and induce other calcium release abnormalities observed in heart failure." (PMID 24141185, 2013). "The many cellular changes that occur in heart failure could lead to changes in the ratio of FKBP12.6/FKBP12 levels in cardiac cells or to conformational changes to RyR2 that affect the relative affinity/efficacy of FKBP12 or FKBP12.6." (PMID 22363773, 2012). "In heart failure, it is possible that an alteration in the dual regulation of RyR2 by FKBP12 and FKBP12.6 may occur." (PMID 22363773, 2012). "Furthermore, in the context of calcium dynamics, it was observed by Arnáiz-Cot and colleagues that the heart failure due to defective RyR2 led to a longer calcium transient decay, longer spark duration, and decreased spark peak, which prove to be consistent in this study." (PMID 39595549, 2024). "Among these variants, rs57938337, rs6683225 and rs6692782 in RYR2 and rs12439006 and rs16958069 in RYR3 are associated with RI in Han Chinese patients with heart failure, suggesting that these variants may be used to identify patients susceptible to CRS in the future." (PMID 37391705, 2023). "The study of the heart-failure model after myocardial infarction in mice showed that RyR2-mediated increased SR-Ca2+ leakage is accompanied by an increase in mitochondrial calcium concentration (Mito-[Ca2+]), suggesting that mitochondrial Ca2+ overload is a key determinant of heart failure." (PMID 35328444, 2022). "Moreover, it has been reported that FKBP12.6 dissociates from RyR2 as heart failure progresses, which may further contribute to increased RyR2 activity." (PMID 34639137, 2021). "Phosphorylation of RyR2 has been reported to reduce the affinity for FKBPs resulting in their dissociation and an increase in the tetramers’ open probability and spark frequency; a phenomenon allegedly responsible for the increased diastolic Ca2+ leak in heart failure." (PMID 31916935, 2020). "Because levels of Zn2+ are altered in heart failure and can be chronically elevated by as much as 30-fold, we next wanted to investigate whether Zn2+ could modulate RyR2 function in the presence of diastolic concentrations of Ca2+ (100 nm) and in the continued presence of 1 mm Mg2+." (PMID 28630041, 2017). "The presented study therefore provides a mechanistic explanation as to how raised levels of intracellular Zn2+ may contribute to the progression of contractile dysfunction and heart failure through the alteration of RyR2 gating, which will result in perturbed Ca2+ release." (PMID 26041778, 2015). "Therefore, RyR2 stabilization may be a novel therapeutic strategy against heart failure and subsequent lethal arrhythmia." (PMID 25614983, 2015). "Overall, this study demonstrates that the (a) combined effect of SERCA and NCX, and the (b) RyR2 dysfunction, along with the downregulation of the cardiomyocyte’s potassium currents, could substantially contribute to Ca2+ mishandling at the spark level that leads to heart failure." (PMID 39595549, 2024).
heart failure (continued). "Moreover, although inhibition of the RyR2 channel in the heart could be a promising anti-heart failure or anti-CPVT1 approach, it could give rise to serious extra-cardiac side-effects because of a strong inhibitory effect of dantrolene on RyR1 and RyR3 channels." (PMID 36982484, 2023). "In these studies, K201 was shown to prevent FKBP12.6 depletion from RyR2 and to restore FKBP12.6 binding to RyR2 in a canine heart failure model." (PMID 35457253, 2022). "This is in clear contrast to ventricular Ca2+ handling remodeling observed in most heart failure models (including humans and SHR), which exhibit increased phosphorylation of RyR2 at both CaMKII and PKA sites." (PMID 36231118, 2022). "The sympathetic nervous system is activated in the early stage of heart failure, which promotes PKA phosphorylation of RyR2 and NO production." (PMID 34639137, 2021). "The rycals are known to stabilize the closed the state of RyR2 and prevent SR Ca2+ leak in animal models of CPVT, ischemia/reperfusion and heart failure." (PMID 30413023, 2018). "There is broad precedent for this general concept, however, as CaMKII mediated RyR2 phosphorylation and PKA mediated phospholamban phosphorylation have established roles in the development of heart failure." (PMID 30520731, 2018). "It is generally considered that the reduced SR Ca2+ content in heart failure is a result of reduced Ca2+ pumping by SERCA and increased SR Ca2+ leak via RyR2." (PMID 28630041, 2017). "We propose that Zn2+ alters the gating of both RyR2 and MG23 and that this is likely to play a key role in diastolic Ca2+ leak leading to the progression of heart failure and the generation of fatal arrhythmias." (PMID 28630041, 2017). "Differential regulation of two calcium release channels (RYR2 and ITPR1) has been reported during end stage heart failure." (PMID 26537877, 2016). "RyR2 is the principal actor of the core mechanism of cardiac ECC, that is, CICR, a highly delicate process where even subtle defects can lead to severe cardiac pathologies, including arrhythmias and heart failure." (PMID 40862759, 2025). "Additionally, CSRP3 and SLMAP that were identified as possibly downregulated are known calcium handling modulators and are dysregulated in heart failure, with downregulation of CSRP3 in a Ryr2 KO mouse model." (PMID 39041002, 2024). "Calcium leakage via the ryanodine receptor type 2 (RYR2) mutant channels or the influx provoked by BCL2/adenovirus E1B interacting protein 3 (BNIP3) overexpression contributes to cardiomyocyte apoptosis and, finally, to heart failure." (PMID 34884857, 2021). "In the sinus node of the heart failure mice, there was no change in the mRNA for various components of the intracellular Ca2+ clock (RyR2, SERCA2, calsequestrin and NCX1) and no change in the mRNA for related Ca2+ channel subunits (Cav1.2, Cavα2δ2)." (PMID 32647133, 2020). "During heart failure, elevated levels of NE in the blood activated PKA and lead to hyperphosphorylation of CaV1.2, which further enhanced Ca2+ induced Ca2+ release through CaV1.2 and RyR2, and resulted in a significant decrease in SERCA2a protein and activity." (PMID 33149749, 2020). "This suggests that when intracellular Zn2+ levels are elevated to levels similar to those in heart failure, RyR2 does not display sub-conductance gating, but rather, the activity of MG23 is increased." (PMID 28630041, 2017). "Recent studies suggest that variants in two calcium handling genes (RyR2 and CASQ2) associated with sudden cardiac death (SCD) and non-sudden cardiac death (NSCD) in subjects with heart failure and coronary artery disease, respectively." (PMID 26196381, 2015). "However, recent studies have found that, under conditions of heart failure, the ability of protein kinase A (PKA) to regulate the phosphorylation of the RyR2 protein is dependent on CaMKII activity." (PMID 23781262, 2013).